TNF (tumor necrosis factor)
Diseases named in the same sentence as TNF in open-access papers (continued):
Sharing a sentence is not in itself a finding about the gene and the disease.
inflammatory bowel disease (continued). "Additionally, in a Danish population, this marker was also associated with response toanti-TNF therapy in patients with inflammatory bowel disease." (PMID 28327786, 2017). "In fact, efficacy of anti-TNF-alpha antibodies in inflammatory bowel diseases (IBD) has been associated with apoptosis modulation in lamina propria mononuclear cells, in particular T cells, through the induction of the intrinsic apoptotic pathway mediated by Bcl-2 family proteins." (PMID 25126549, 2014). "Loss of response (LoR) is a major limitation of anti-tumor necrosis factor (anti-TNF) therapy in inflammatory bowel disease (IBD)." (PMID 41388917, 2025). "TNF-α is a key proinflammatory cytokine involved in gut and brain inflammation; its overproduction is linked to inflammatory bowel disease (IBD), neurodegenerative disorders, and mood disorders by promoting blood−brain barrier disruption and neuroinflammation." (PMID 40077713, 2025). "Is anti–tumor necrosis factor (TNF) therapy associated with kidney disease progression or mortality among patients with new-onset inflammatory bowel disease (IBD)?" (PMID 38625700, 2024). "While effective in preventing the complications of inflammatory bowel disease (IBD), anti-TNF has been associated with an increased risk of infection." (PMID 37554999, 2023). "Loss of response to anti-tumor necrosis factor drugs in patients with inflammatory bowel disease (IBD) is frequent and, in case of low drug levels, treatment intensification is recommended." (PMID 36785555, 2023). "Partial or complete loss of anti-TNF drugs’ impact occurs in patients with inflammatory bowel diseases (IBD), rheumatoid arthritis, and psoriasis." (PMID 36013252, 2022). "Anti‐drug antibodies are associated with treatment failure to anti‐TNF agents in patients with inflammatory bowel disease (IBD)." (PMID 36039036, 2022). "The interleukin-6 family cytokine, oncostatin-M (OSM) has been associated with response to tumor necrosis factor-α antagonists (anti-TNFs) in small cohorts of patients with inflammatory bowel disease (IBD)." (PMID 35075155, 2022). "Interestingly, some of these mediators such as IL-6 and TNF-α are involved in the pathogenesis of inflammatory bowel disease, promoting gut damage and loss of intestinal barrier integrity, while IL-10 reduces the inflammation typically associated with this pathology." (PMID 35854319, 2022). "Furthermore, Butyricicoccus are butyrate-producing bacteria associated with decreased intestinal myeloperoxidase, tumor necrosis factor-α and interleukin-12 levels in inflammatory bowel disease rat models, contributing to reduced pro-inflammatory potential in the gut microenvironment." (PMID 35656540, 2022). "Tumour necrosis factor (TNF)-alpha has been widely implicated in inflammatory bowel disease (IBD), with anti-TNF biologics constituting an integral component of IBD pharmacotherapy." (PMID 36289474, 2022). "Here, we evaluated the performances of a Model Informed Precision Dosing (MIPD) Tool in forecasting trough Infliximab (IFX) levels in association with disease status and circulating TNF-α in patients with Inflammatory Bowel Diseases (IBD)." (PMID 35743387, 2022). "Inflammatory bowel disease (IBD) is associated with intestinal epithelial barrier dysfunction and elevation of proinflammatory cytokines such as TNF-α." (PMID 35741912, 2022). "In addition, it has also been linked to the stimulation of TNF production in vitro from peripheral blood mononuclear cells of healthy patients, as well as a higher circulating IgG response in patients affected by inflammatory bowel disease." (PMID 33416489, 2021). "Anti-tumor necrosis factor (TNF) treatment for inflammatory bowel disease (IBD) increases the risk of tuberculosis (TB) infection." (PMID 34670529, 2021).
inflammatory bowel disease (continued). "Furthermore, TNF-α treatment increased the expression of genes encoding various proinflammatory cytokines such as IL-6, IL-8, IL-1β, and IL-17C, involved in the progression of inflammatory bowel disease." (PMID 34208517, 2021). "Intestinal inflammation and epithelial injury are the leading actors of inflammatory bowel disease (IBD), causing an excessive expression of pro-inflammatory cytokines such as TNF-α." (PMID 32099606, 2019). "The cytokine tumour necrosis factor alpha (TNFα) plays a central pathogenic role in inflammatory bowel disease (IBD)." (PMID 29563546, 2018). "In mammalian models of inflammatory bowel disease (IBD), endotoxin and flagellin cause intestinal inflammation through upregulation of tumor necrosis factor (TNF)-α expression." (PMID 30174665, 2018). "This receptor has been largely associated with inflammatory diseases, including inflammatory bowel diseases, and it can signal through caspase-1 to cause the production of pro-inflammatory IL-1β and IL-18, as well as TNF-α and nitric oxide, from inflammatory cells." (PMID 29167643, 2017). "Under pathological conditions, excessive TNFα activity can lead to chronic inflammation, contributing to diseases such as inflammatory bowel disease and other autoimmune disorders." (PMID 41551713, 2026). "Tumor necrosis factor-alpha (TNF-α) inhibitors are extensively utilized in inflammatory bowel disease (IBD)." (PMID 41884829, 2026). "Background/Objectives: Tumor necrosis factor alpha (TNF-alpha) plays a key role in systemic inflammation in multiple disorders, including inflammatory bowel diseases (IBDs)." (PMID 41682723, 2026). "We report a cutaneous M. decipiens infection in a patient in France who had inflammatory bowel disease being treated with anti-tumor necrosis factor-α therapy." (PMID 41612605, 2026). "Monoclonal antibodies that block pro-inflammatory cytokine tumor necrosis factor-alpha (TNF-α) are effective therapy for inflammatory bowel diseases (IBD)." (PMID 41985594, 2026). "Infliximab, an anti-TNF- α monoclonal antibody, is widely used in the treatment of inflammatory bowel disease but shows variable effectiveness due to interindividual pharmacokinetic diversity." (PMID 41678027, 2026). "Anti‐inflammatory agents, including TNFα and anti‐α4β7 integrin antagonists, effectively restored optimal IR‐TCF7high expression in inflammatory bowel disease patients who exhibited a MAS‐1high profile at baseline." (PMID 40264357, 2025). "Due to the limitations of clinical trials, the occurrence of infective pneumonia in patients with inflammatory bowel disease using tumor necrosis factor-α(TNF-α) inhibitors remains uncertain." (PMID 40763141, 2025). "Background/Objectives: Tumor necrosis factor antagonists (anti-TNFs) have been shown to be an effective treatment for inflammatory bowel disease (IBD)." (PMID 40004589, 2025). "For instance, the advent of monoclonal antibodies targeting tumor necrosis factor-alpha (TNF-α) or integrins has revolutionized inflammatory bowel diseases management, offering clinical remission for patients unresponsive to conventional therapy." (PMID 40681504, 2025). "While inflammatory bowel diseases (IBDs) can be treated with anti-TNF agents and ustekinumab, IL-17 antagonists may cause new-onset or paradoxically flare a pre-existing IBD." (PMID 40109802, 2025). "The marked reduction in TNF-α levels is equally significant, as this cytokine serves as a central mediator in the pathogenesis of inflammatory bowel diseases." (PMID 41465478, 2025). "The anti-inflammatory effect of SA was reported in inflammatory bowel disease, as it decreased inflammatory markers such as NF-κB, TNF-α, and IL-1β." (PMID 40426893, 2025). "The pro-inflammatory cytokine tumor necrosis factor-α(TNF-α) is the mediator of inflammatory bowel disease." (PMID 40763141, 2025).
inflammatory bowel disease (continued). "This subset, characterized by IL-17 A, IL-2, TNF-α, and IFN-γ secretion, has been implicated in inflammatory diseases such as Crohn’s disease and inflammatory bowel disease." (PMID 41194200, 2025). "Although this study provided valuable insights into infective pneumonia following TNF-α inhibitor use in patients with inflammatory bowel disease, it was essential to acknowledge the limitations of the FAERS database itself." (PMID 40763141, 2025). "KEGG analysis indicated enrichment in cytokine-cytokine receptor interaction, cell adhesion molecules, chemokine signaling pathway, NOD-like receptor signaling pathway, TNF signaling pathway, IL-17 signaling pathway, and inflammatory bowel disease." (PMID 40115777, 2025). "Anti-TNF therapies (e.g., infliximab, adalimumab) promote mucosal healing in inflammatory bowel disease and reduce corticosteroid use, maintaining CD remission." (PMID 40843056, 2025). "For example, anti–TNF-α drugs in inflammatory bowel disease have improved not only the condition but also coexisting mood disorders." (PMID 40275936, 2025). "Anti-tumor necrosis factor (TNF)-alpha inhibitors are commonly used in the treatment of inflammatory bowel disease (IBD)." (PMID 41472914, 2025). "For this reason, anti-TNF-α therapy is widely used in the clinical management of inflammatory bowel diseases, including ulcerative colitis and Crohn’s disease." (PMID 40428786, 2025). "In the TNF-α pathway, inhibitors such as Infliximab and Adalimumab are widely used in the clinical management of inflammatory bowel disease." (PMID 41376630, 2025). "The causes of inflammatory bowel disease (IBD) are complex and may involve chronic systemic inflammation, with factors such as tumour necrosis factor‐α (TNF‐α) and interleukins (ILs) potentially contributing to the destruction of the intestinal epithelium." (PMID 39993996, 2025). "Infliximab, a chimeric monoclonal IgG1 antibody against tumor necrosis factor (TNF), was the first biologic approved for the treatment of moderate to severe inflammatory bowel disease (IBD) in adults over 20 years ago." (PMID 41116055, 2025). "Meanwhile,TNF-α inhibitors have made significant advancements in treating inflammatory bowel disease and other illnesses." (PMID 40356970, 2025). "In inflammatory bowel disease, TNF-α has been shown to block the expression of M2-related genes in macrophages and polarize them away from the immunosuppressive M2 phenotype." (PMID 40109347, 2025). "Background/Objectives: Patients suffering from inflammatory bowel diseases (IBDs) undergoing treatment with anti-TNF antibodies mount a diminished humoral immune response to vaccination against SARS-CoV-2 compared to healthy controls." (PMID 40573926, 2025). "In the comparison between DSS-BI and DSS groups, the most enriched KEGG pathways were Cytokine-cytokine receptor interaction, IL-17 signaling pathway, TNF signaling pathway, Inflammatory bowel disease and so on." (PMID 41036227, 2025). "Studies in patients with inflammatory bowel disease reported the role of Enterobacterales in increasing the levels of IL-8, tumor necrosis factor (TNF)-α, and IL-1β." (PMID 40218236, 2025). "Currently, the main TNF-α inhibitors used to treat inflammatory bowel disease are infliximab, adalimumab, certolizumab pegol, and golimumab." (PMID 40763141, 2025). "In conclusion, TNFα inhibitor-induced alopecia is a rare adverse event in children, occurring mainly in adolescents with inflammatory bowel diseases." (PMID 40481366, 2025). "In the patient population diagnosed with inflammatory bowel disease, the prevalence of ANAs is approximately 14%, while seroconversion occurs in approximately 28% of individuals undergoing immunosuppressive anti-TNF therapy." (PMID 40573926, 2025). "Support for this comes from epidemiological reports that anti-TNF therapy in inflammatory bowel disease patients and ibuprofen use in the general population are associated with a lower incidence of PD52,53." (PMID 40341772, 2025).
inflammatory bowel disease (continued). "Central to the network map are the following keywords: inflammatory bowel disease (3707 occurrences), infliximab (3305), Crohn’s disease (3205), ulcerative colitis (2267), maintenance therapy (1744), and anti-TNFα (1262)." (PMID 40143091, 2025). "Upon activation, it induces the expression of pro-inflammatory cytokines such as interleukin (IL)-6, IL-12, IL-23, and tumor necrosis factor-α (TNF-α), all of which are central to the inflammatory cascade in inflammatory bowel disease (IBD)." (PMID 41007813, 2025). "The involvement of TNF‐α in inflammatory bowel disease (IBD) has been well established, with clinical studies reporting elevated levels in IBD patients—31% higher in UC and 80% higher in CD compared to healthy controls." (PMID 41244339, 2025). "In addition, TNF-α is associated with the pathophysiology of arthritis, inflammatory bowel disease (IBD), and some specific types of cancer." (PMID 41305639, 2025). "Despite the availability of newer therapeutic options, anti-TNF-α agents remain the cornerstone of initial biologic treatment in inflammatory bowel disease (IBD)." (PMID 40806407, 2025). "The emergence of anti-TNF agents has revolutionized the management of inflammatory bowel disease, yet a significant proportion of patients experience primary non-response or secondary loss of response due to immunogenicity." (PMID 40806407, 2025). "Background/Objectives: Tumor necrosis factor alpha (TNF-α) is the key inflammatory cytokine involved in the pathogenesis of inflammatory bowel diseases (IBDs)." (PMID 40149645, 2025). "Gene Set Enrichment Analysis (GSEA) supported these observations by revealing increased activity in TNF signalling, NF‐κB signalling, and the inflammatory bowel disease pathway in UC samples relative to controls." (PMID 40903840, 2025). "Anti-TNF-α therapy is widely used for inflammatory bowel disease (IBD), but response rates vary, and long-term efficacy declines in many patients." (PMID 41373818, 2025). "As the first anti-TNFα drug developed for inflammatory bowel disease (IBD), infliximab (IFX) effectively alleviates disease symptoms." (PMID 40607383, 2025). "While infliximab is commonly used for treating inflammatory conditions such as inflammatory bowel disease, paradoxical sarcoidosis secondary to tumor necrosis factor alpha (TNF-α) inhibitors is a rare complication." (PMID 40351964, 2025). "Fexofenadine, known as a novel inhibitor of TNF‐α signaling, exhibits therapeutic effects on inflammatory bowel disease." (PMID 40630428, 2025). "Biologic agents, such as monoclonal antibodies targeting tumour necrosis factor (TNF), have become the gold standard in the treatment of inflammatory bowel disease (IBD)." (PMID 39859084, 2025). "Butyrate supports remission in inflammatory bowel disease by reducing Interleukin (IL) 6 and TNF-α levels." (PMID 41375615, 2025). "Future research should aim to address these limitations to provide more robust evidence regarding the safety profile of anti-TNF agents in pediatric inflammatory bowel disease." (PMID 39861147, 2025). "Inflammatory bowel disease patients should be screened for tuberculosis infection before starting treatment with TNF-α inhibitors and thoroughly monitored for tuberculosis infection throughout treatment." (PMID 40763141, 2025). "For the first time, we demonstrate that FPE protects intestinal enterocytes (Caco-2) and colonocytes (T84) from inflammation and oxidative stress induced by TNF-α, a key cytokine in the pathogenesis of inflammatory bowel diseases." (PMID 41417098, 2025). "The safety of anti-TNF-α agents during pregnancy has been well documented, primarily based on evidence from their use in pregnancies complicated by inflammatory bowel disease." (PMID 40236588, 2025). "TNF antagonists, available as anti-TNF monoclonal antibodies or TNF fusion proteins, have become the most important treatment for inflammatory bowel disease." (PMID 40763141, 2025).
inflammatory bowel disease (continued). "These include the use of biologics and small molecules that modulate inflammatory cytokines (e.g., TNF-α, IL-6, IL-17), many of which are already used in conditions such as inflammatory bowel disease." (PMID 41020835, 2025). "Preliminary studies show that tumor necrosis factor-α (TNF-α) mediates inflammatory responses in inflammatory bowel disease." (PMID 40230717, 2025). "TNF alpha and interleukins (ILs), proinflammatory cytokines, play a significant role in the pathogenesis of inflammatory bowel diseases." (PMID 40589768, 2025). "In the reviewed literature, 8/11 patients received corticosteroids without a consistent regimen; one patient also received mycophenolate mofetil and anti-TNF-a therapy in an inflammatory bowel disease context." (PMID 38807591, 2024). "In the context of immunocompromised cohorts, a previous study assessed patients with inflammatory bowel disease well known to be characterised by gut microbiome dysbiosis, who were receiving anti-TNF immunomodulators." (PMID 38316462, 2024). "The local expressions of IL1, IL6 and TNFα were reported mainly after the exposure of pigs to a bacterial or viral infection and even in humans in the form of inflammatory bowel diseases." (PMID 39409727, 2024). "Many patients with inflammatory bowel disease (IBD) experience a loss of effectiveness to biologic therapy (i.e., anti-TNF therapy, etc.)." (PMID 38534206, 2024). "By acting on the TNF signaling pathway, cancer signaling pathway, hepatitis B, and other signaling pathways to play a role in the treatment of inflammatory bowel disease." (PMID 39086391, 2024). "TNF-α is involved in the pathophysiology of inflammatory bowel disease, contributing, together with IFN-γ, to epithelial cell apoptosis." (PMID 39335466, 2024). "Utilising TDM to guide treatment decisions for patients who are not responding adequately to therapy has become an established part of treatment with anti-TNF therapy in inflammatory bowel disease." (PMID 38399538, 2024). "IL-8 and TNF-α are proinflammatory cytokines, and their upregulation is generally involved in inflammatory bowel disease." (PMID 39555560, 2024). "Antitumor necrosis factor (anti-TNF) agents have revolutionized the care for patients with inflammatory bowel disease (IBD) and are commonly prescribed biologics." (PMID 39525292, 2024). "MAdCAM-1 is constitutively expressed by intestinal endothelial cells, and its expression is upregulated on inflamed venules in chronic inflammatory diseases (e.g., inflammatory bowel disease) and induced by TNF-α and IL-1β." (PMID 38338944, 2024). "The introduction of anti-tumor necrosis factor α (TNFα) biologics significantly innovated inflammatory bowel disease (IBD) treatment and increased medical costs." (PMID 39114362, 2024). "Inflammatory cytokines, such as tumor necrosis factor-α (TNF-α) and interleukin-6 (IL-6), in intestinal epithelial cells significantly contribute to inflammatory bowel disease (IBD) and colorectal cancer (CRC)." (PMID 39451248, 2024). "In CRC associated with inflammatory bowel diseases (IBD), stimulation of the tumor necrosis factor (TNF) receptor 1 by TNF-α led to a NF-κB activation and c-Jun-dependent transcriptional upregulation of MACC1." (PMID 39580452, 2024). "For example, LPS, adhesins, and other virulence factors in the periodontal bacterium Fusobacterium nucleatum-derived EVs interact with Toll-like receptor (TLR)-4 and induce the expression of IL-8 and TNF-α in patients with inflammatory bowel disease (IBD)." (PMID 39698538, 2024).